BRCA1 (BRCA1 DNA repair associated)
Diseases named in the same sentence as BRCA1 in open-access papers (continued):
Sharing a sentence is not in itself a finding about the gene and the disease.
tumor (continued). "This is consistent with low-level mosaic BRCA1 methylation in normal breast cells and/or other normal cells present in the tumor biopsies." (PMID 38053165, 2023). "BRCA1 and BRCA2 are crucial components of the HR pathway and have been identified as major tumor susceptibility genes since pathogenic mutations in these genes result in defective HR repair." (PMID 37894343, 2023). "Down-regulated genes belong to the class of oncogenes (Akt1, Ccnd1, Myb, and Src) and tumor suppressors (Brca1, Brca2, and Mlh1)." (PMID 37297299, 2023). "BRCA1/2 alterations are most frequently bi-allelic in tumor types that have demonstrated clinical sensitivity to PARPi monotherapy, including ovarian, breast, prostate, and pancreatic cancer." (PMID 37803017, 2023). "Both studies showed that the iTME in a BRCA1/2-mutated setting had greater frequencies of CD8 T cells, macrophages, and PD-L1-expressing tumor cells and fibroblasts than in the BRCA1/2 wild-type setting." (PMID 36635516, 2023). "Another tumor that was GI-positive with Myriad MyChoice had both a splice-disrupting variant in RAD51C and a pathogenic BRCA1 variant." (PMID 38067228, 2023). "In the first case, a tumor is considered to be HRD positive if the %LOH value is >16% and/or a BRCA1/2 mutation is detected." (PMID 37761329, 2023). "The gene is located in a region of chromosome 17q21.1 that is very close to the BRCA1 tumor suppressor gene." (PMID 37915049, 2023). "BARD1 has homology BRCT domain of BRCA1, and the stable interaction between BRCA1 and BARD1 is essential for BRCA1 as a tumor suppression." (PMID 36593954, 2023). "ER-negative BC is the predominant tumor subtype in BRCA1 PV carriers; therefore, these studies highlight the strong association of BC subtype-specific PRS with the BC risk." (PMID 37296919, 2023). "Most likely, this patient harbored two independent subclones of BRCA1-methylated normal cells, with one clone giving rise to the tumor cells." (PMID 38053165, 2023). "Functional mutations in BRCA1 and BRCA2 have been identified in tumor cells, impairing their HRR capacity." (PMID 37958290, 2023). "Combinations with a STING agonist resulted in further improved durable tumour regression and significant improvements in survival outcomes in murine tumour models of BRCA1/2 wild-type TNBC." (PMID 37582853, 2023). "Significant differences in tumor morphology, peripheral features, posterior echoes, echogenic foci, and vascularity were observed between BRCA1 and BRCA2 tumors." (PMID 36905492, 2023). "The CtIP protein was originally identified on the basis of its association with the CtBP transcriptional co-repressor and the BRCA1 tumor suppressor." (PMID 38067190, 2023). "Evidence suggests that CDK4/6 inhibitors in combination with endocrine therapy can induce a synthetic lethal effect on BRCA1/2 mutant and HR+ tumor cells." (PMID 37444415, 2023). "Our study has a clear strength since it focused on a cohort of patients with a proven tumor BRCA1 promoter hypermethylation." (PMID 36112334, 2023). "Two or more tumour samples were tested from 29 patients due to prior complete assay failure (tumour BRCA1/2 and GIS testing; 23/29 patients) or because the patient was mistakenly tested twice (6/29 patients)." (PMID 38201604, 2023). "To further examine the finding that patients with somatic BRCA2 PVs were older than those with somatic BRCA1 PVs, we analysed tumour sequencing data from an independent patient cohort from the INOVATe study." (PMID 36805919, 2023).
tumor (continued). "Three non-BRCA1/BRCA2 tumours also had a HRDetect score of > 0.99 and were classified as having BRCA1/BRCA2-deficient tumours." (PMID 37316882, 2023). "The high concordance in methylation status between tumor and normal tissues suggests that there is a consistent regulatory pathway driving BRCA1 epigenetic silencing in both types of tissues." (PMID 37761820, 2023). "Our findings demonstrated a higher prevalence of BRCA1 promoter hypermethylation in malignant breast tumors (MBTs) and normal adjacent tissues (NATs) compared to benign breast lesion samples." (PMID 37761820, 2023). "Previously, the most classic finding was that tumor cells with BRCA1/2 dysfunction were highly sensitive to PARPi alone, namely, “synthetic lethality”." (PMID 37442994, 2023). "Three germline BRCA1/2 large genomic rearrangements were detected in germline and tumour DNA using Myriad’s myChoice® CDx, including BRCA1 Exon 9-12 deletion (GIS 56), BRCA1 Exon 17 deletion (GIS 70) and BRCA2 Exon 14-16 deletion (GIS 36)." (PMID 36765687, 2023). "Previous studies have certainly identified an association between BRCA1 loss and higher intra-epithelial CD8+ numbers, whilst tumours marked by fold-back inversions contain fewer CD8+ cells." (PMID 37474499, 2023). "In this subgroup, four out of six patients harbored BRCA1 methylation in their tumor tissue, all revealing concordant WBC methylation." (PMID 38053165, 2023). "In this research set, ratios of BRCA1 and BRCA2 circRNAs/mRNAs were significantly lower in the tumor breast tissue compared to normal tissue (p = 1.6 × 10−9 and p = 4.4 × 10−5 for BRCA1 and BRCA2, respectively)." (PMID 37046838, 2023). "The rate of BRCA1 promoter methylation in NATs has been reported to vary depending on the distance between the normal tissue site and the tumor." (PMID 37761820, 2023). "This resulted in a very strong separation of tumours with all BRCA1 and BRCA2 positive tumours having a HRDetect score of > 0.99." (PMID 37316882, 2023). "The mutation landscape of HRR-related genes revealed several possible recurrent hotspot driver mutations in ARID1A, ATRX, ATM, and BRCA1/2, including R1989* in ARID1A, which was carried by over 30 tumor patients." (PMID 37264024, 2023). "BRCA1 and 2 genes are considered to be tumor suppressor genes, and their inactivation is responsible for a predisposition to breast or ovarian cancer." (PMID 36831640, 2023). "This indicates that under prolactin stimulation, STAT5 binds to BRCA1 to induce a dominant-negative phenotype that inhibits a critical tumor-suppressive function of BRCA1 through the suppression of p21 transcription." (PMID 37173951, 2023). "Efficacy in BRCAWT tumours is likely due to BRCAness, a phenotype similar to BRCAMUT, with a defect in homologous recombination repair, but actually lack the mutation in BRCA1/2." (PMID 36941406, 2023). "Since BRCA1 is a tumor suppressor, and is directly involved in the double-strand break (DSB) repair process, it is not surprising that the mutation status of this gene serves as a prediction marker for a high risk of carcinogenesis." (PMID 36902416, 2023). "Loss of BRCA1 or BRCA2 function in normal cells leads to growth defects that, combined with a subsequent loss of other DDR mediators, promote tumour development." (PMID 37644384, 2023). "Lastly, the patient designated as 20X0127, carrying a germline BRCA1 deletion of exons 18 and 19, showed an abnormal splice junction from exons 17 to 20 in both their normal and tumor breast tissues." (PMID 37046838, 2023).
tumor (continued). "Other authors have also shown that BRCA1 promotes cell cycle arrest and tumor growth suppression through the induction of the cyclin-dependent kinase 2 (CDK2) inhibitor p21." (PMID 37444415, 2023). "PARP inhibitor resistance in BRCA1−/− tumours develops through the restoration of HR via numerous mechanisms, including loss of 53BP1 and re-expression of wild-type BRCA1." (PMID 36980782, 2023). "In summary, we established a novel link between the deposition and maintenance of chromatin structure during the S phase and the BRCA1 tumour suppressor pathway, which is required for replication fork stability and genome integrity." (PMID 37364916, 2023). "BRCA1, a major tumor suppressor in BC, regulates numerous pathways resulting in anticarcinogenic functions." (PMID 37109525, 2023). "To evaluate the potential of using DNA-PKcsi to treat olaparib-resistant BRCA1-mutated ZNF251KD cells in vivo, we conducted an experiment where we treated tumor-bearing mice with PIK-75 and/or olaparib." (PMID 37066268, 2023). "If a patient was identified with any P/LP variants of BRCA1, BRCA2, or PALB2 within the tumor, clinical germline testing (CGT) would be performed." (PMID 38098088, 2023). "We found six heterozygous variants predicted to alter splicing; two in DNA repair-associated genes (BRCA1 and BAP1) and four in tumor suppressor genes (ARHGEF10L, ELL, MYH9, and NCOR2)." (PMID 37234870, 2023). "In conclusion, our study provides evidence that tumour sequencing through ION Torrent is a reliable tool for detecting BRCA1/2 germline PVs." (PMID 37179432, 2023). "P/LP variants in certain genes (e.g., BRCA1/2, SDHB) identified in tumor-only sequencing of GISTs were almost exclusively germline in origin." (PMID 36593350, 2023). "They not only assist in exploring the intricate genetic interactions between BRCA1 and other pathways but also reveal specific biochemical functions of BRCA1 that are crucial for its tumor suppressor activity." (PMID 37762577, 2023). "The leading biomarkers that led to treatment recommendations were tumor mutational burden‐high (TMB‐H) (n = 32), ERBB2 amplification (n = 24), BRAF V600E (n = 16), and BRCA1/2 alterations (n = 32)." (PMID 36251535, 2023). "En relación a la edad de diagnóstico del tumor, se ha observado que la mediana en portadores BRCA1/BRCA2 afectados de cáncer de mama fue superior a los 40 años." (PMID 38075173, 2023). "In LGG, mutations in BRCA1 and BRCA2 have been associated with a higher risk of tumor recurrence and a poorer prognosis." (PMID 37660060, 2023). "This newfound role of BRCA1 in modulating GOT2 expression introduces yet another noteworthy facet to its role as a tumor suppressor." (PMID 37762577, 2023). "In the TCGA dataset, the connections between the ERGRS and some clinic pathology characteristics (survival status, age, tumor stage, tumor grade, therapy type, and BRCA1 type) were analyzed." (PMID 36726489, 2023). "The tumor suppressor BRCA1, a potent NRF2 binding protein, restores the stability of and activates NRF2 by inhibiting the Keap1-mediated NRF2 ubiquitination." (PMID 37571283, 2023). "For instance, markers of both leukocyte activation (CD44) and exhaustion (LAG3) were also highest in the Brca1-null tumours." (PMID 38017453, 2023). "The genetic landscape, especially mutations in BRCA1 and BRCA2, plays a pivotal role in BC development by disrupting the normal tumor-suppressive functions, thereby propelling unchecked cellular proliferation and genomic instability." (PMID 38066539, 2023).
tumor (continued). "Once the BRCA1 or BRCA2 gene is mutated, the tumor suppression effect will be impaired, hence accelerating cancer development and progression." (PMID 38068930, 2023). "For BRCA1, the average ratio of circRNAs/mRNAs was significantly lower in tumor tissue samples compared to normal adjacent mammary tissue samples (1.14 vs. 1.89, p-value = 1.6 × 10−9)." (PMID 37046838, 2023). "Pathogenic mutations in BRCA1 or BRCA2 genes were detected in 2% and alterations in other HRR-related genes in 8% of evaluated tumor samples." (PMID 38201431, 2023). "SEALigHTS deciphered the BRCA1 and BRCA2 backsplicing landscape in normal and tumor breast tissues and identified not only the already described circRNAs but also 10 and 5 novel ones for BRCA1 and BRCA2, respectively." (PMID 37046838, 2023). "Cell viability analyses showed that NCT-505 and olaparib can synergistically reduce tumor cell viability in OV35 and OV39 HGSOC tumor organoids, which possess BRCA2 and BRCA1 mutation, respectively, as well as positive ALDH1A1 expression." (PMID 37429899, 2023). "BAP1 was discovered during a protein interaction screening for BRCA1 and has been shown to collaborate with BRCA1 in tumor suppression in cultured cells." (PMID 36765733, 2023). "Tumor HRD status was determined by Miriad myChoice CDx testing, which is designed based on germline/somatic BRCA1/2 mutations and/or positive genomic instability scores using DNA isolated from formalin-fixed paraffin-embedded (FFPE) tumor tissues." (PMID 37664647, 2023). "Among non-BRCA1/BRCA2 tumours, the RNA classifier identified 5/23 (22%) tumours with BRCAness compared to HRDetect predicting 3/23 (13%) tumours as having BRCAness." (PMID 37316882, 2023). "Although BAP1 was originally identified as a protein associated with the BRCA1 tumor suppressor, the significance of the BAP1 and BRCA1 interaction has thus far remained unclear." (PMID 37009801, 2023). "Of the 3 olaparib responders, PDX tm168 and o10047 were BRCA1-Mut and b4122 was BRCA1-Me, but established from a treatment naïve tumor." (PMID 37007122, 2023). "In our MPM cohort, tumor samples with a low number of RAD51 foci displayed a low number of BRCA1 foci, likely corroborating defects in the HR repair pathway." (PMID 37686585, 2023). "In this study, we found the role of BRCA1 in tumor suppression and DNA damage response, including DNA damage-induced cell cycle checkpoint activation and DNA damage repair." (PMID 36785669, 2023). "It is of note that no pre-treatment biopsy was available for the tumors that had undergone NACT, hence, BRCA1 promoter methylation was determined after NACT on these tumor samples." (PMID 37007122, 2023). "BRCA1 and BRCA2 mutation status and TMB were analyzed in tumor DNA using next-generation sequencing." (PMID 37446361, 2023). "The biochemical function of BRCA1 that is perhaps most essential for its tumor suppression activity is the regulation of repair of DNA double strand breaks via the homology directed repair (HDR) mechanism." (PMID 37917606, 2023). "In this genomic analysis of the ABRAZO trial, we demonstrate that tumor-only BRCA1/2 sequencing has high sensitivity for gBRCA1/2mut." (PMID 37803017, 2023).
tumor (continued). "One of the two patients achieving an objective tumour response (OTR) had BRCA1 methylation, while the best response for the remaining patients with HRR-altered tumours was stable disease for at least four months." (PMID 37365284, 2023). "In this study, we show that WEE1 inhibition can sensitise BRCA1/2 wild-type TNBC to PARP inhibitors resulting in synergistic anti-tumour efficacy with increased DNA damage, apoptosis, replication stress, and STING pathway activation." (PMID 37582853, 2023). "Samples with biallelic loss of FANCC or FANCI were scored as fHRP, whereas one tumor with biallelic loss of FANCM (and intact BRCA1/2) was fHRD." (PMID 36805632, 2023). "The study group comprised 367 patients who successfully underwent both tumour and germline BRCA1/2 testing." (PMID 38201604, 2023). "In this study, we show intraindividual allele concordance between mosaic BRCA1 methylation in normal blood cells and BRCA1 methylation, clonally expanded, in tumor tissue." (PMID 38053165, 2023). "Next, we generated empty- and Gata3-expressing p18mt;Brca1+/− tumor cells, as previously reported, and performed similar analysis as for p18mt;Gata3+/− tumor cells." (PMID 37353480, 2023). "Patients underwent local germline BRCA1/2 testing, whilst tumour testing was performed using the myChoice® companion diagnostic (CDx; Myriad Genetics, Inc., Salt Lake City, UT, USA)." (PMID 38201604, 2023). "Tumor regression and increased overall survival in patients with acquired PARP inhibitors resistance were observed in patients with BRCA1/2 mutations and BRCA wild-type models." (PMID 36611214, 2023). "We demonstrate that combined PARP and WEE1 inhibition are synergistic in controlling tumour growth in BRCA1/2 wild-type TNBC preclinical models." (PMID 37582853, 2023). "For HER2-negative tumors expressing ER ≥ 10%, six out of 221 revealed BRCA1 tumor methylation with only three of these patients revealing concordant WBC BRCA1 methylation." (PMID 38053165, 2023). "Another Polθ inhibitor, ART558, also exhibited synthetic lethality in BRCA1- or BRCA2-mutant tumor cells and enhanced the cytotoxicity of PARPi29." (PMID 37429899, 2023). "Tumour BRCA1/2 testing was performed using the next-generation sequencing (NGS)-based myChoice® companion diagnostic (CDx; Myriad Genetics, Inc.)." (PMID 38201604, 2023). "NVB treatment significantly reduced BRCA1-deficent geneticallyengineered mouse model derived tumors and prolonged the overall survivalof tumor-bearing mice." (PMID 37134182, 2023). "Increased cytotoxicity and anti-tumor activity were observed in cell lines and mice tumor models with defects in BRCA1/2, ATM, or other genes involved in DNA repair after treatment with olaparib, and this was linked with platinum responsiveness." (PMID 36077867, 2022). "The data revealed that both mRNA and protein levels were elevated in Brca1-MT MG and tumor tissues compared with controls." (PMID 35304461, 2022). "For many years, BRCA1 has been well established as a tumor suppressor, and it functions primarily by maintaining genome integrity." (PMID 35453307, 2022). "The sensitivity of tumors with HRR mutations (HRRm), including BRCA1, BRCA2, PALB2, and RAD51C, to PARPi has been reported in preclinical research, as well as clinically, across tumor types." (PMID 36970052, 2022). "The BRCA1-mutated model, PDX #56, displayed a mixed response to the LCL161/olaparib combination with two out of five tumours showing stabilisation." (PMID 35501389, 2022). "The aim of this study was to establish a uniform procedure for the detection and interpretation of BRCA1 and BRCA2 alterations in different BRCA associated tumor diseases and to facilitate routine diagnostics." (PMID 35251494, 2022).